YAP1 (Yes1 associated transcriptional regulator)
Diseases named in the same sentence as YAP1 in open-access papers (continued):
Sharing a sentence is not in itself a finding about the gene and the disease.
tumor (continued). "YAP1 modulates CRC progression and metastasis through the regulation of oncogenic signaling cascades, cytokine networks, and suppression of M2‐type tumor‐associated macrophage (TAM) polarization." (PMID 41152153, 2025). "Together, our results uncover a novel tumor‐promoting role of DUB3 in CRC mainly through stabilizing YAP1." (PMID 39968498, 2025). "SPP1+ macrophages co-localize with Liver-CSCs and secrete vitronectin (VTN), activating the integrin αvβ5/AMP-activated protein kinase (AMPK)/Yes-associated protein 1 (YAP1)/SOX4 pathway to drive stemness and tumor progression." (PMID 41438763, 2025). "further demonstrated that interfering with SNHG15 activates MST1 and LATS1 within the Hippo pathway, thereby reducing YAP1 expression and inhibiting tumor progression." (PMID 41234719, 2025). "In this study, we investigated how oHSV-induced IGF1R/YAP1 signaling influences feedback pro-survival and proliferative pathways in tumor cells and evaluated the therapeutic potential of combining IGF1R blockade with oHSV and RTx." (PMID 41510300, 2025). "Consistent with our previous study, we observed similar results that Yap1 silencing in MC38 CRC cells reduced metastatic tumor growth enhanced by HFD feeding." (PMID 39946200, 2025). "In this model, tumor LDHA was shown to upregulate CCL2/CCL7 via the ERK → YAP1/STAT3 pathway, thereby recruiting macrophages." (PMID 41463052, 2025). "Advanced tumor stage cases displayed higher levels of cytoplasmic YAP1 expression (Mann–Whitney U test, I versus II/III/IV, p = 0.032)." (PMID 40649713, 2025). "β-catenin activates the mTORC1 signalling pathway by binding to Yes-associated protein 1 (YAP1), promoting the expression of the amino acid transporter SLC38A1, which enhances tumor metabolism and growth." (PMID 40438141, 2025). "In terms of therapeutic response, the current evidence supports a potential role of YAP1 in chemoresistance across different tumor types." (PMID 40731926, 2025). "In TNBC, where Hippo pathway dysregulation is common, YAP1 activation is thought to contribute to tumor progression and therapeutic resistance, making its regulatory mechanisms an area of intense interest." (PMID 41226688, 2025). "In this study, scRNA‐seq results revealed that the expressions of GLS, PPP1R13L, MYB, and YAP1 were significantly elevated in tumor epithelial cells." (PMID 41152153, 2025). "Huh6 cells were subcutaneously transplanted into nude mice, which were monitored weekly for tumor size while receiving treatments with the YAP1 inhibitor Verteporfin, the NAT10 inhibitor Remodelin, and the G6PD inhibitor Fluasterone." (PMID 40303290, 2025). "For instance, Verteporfin, bis-aryl hydrazine scaffold and VGLL4 peptides were previously reported to inhibit the interaction between YAP1 and TEADs and display a tumor-suppressive effect in several cell and animal models." (PMID 39827153, 2025). "We also found that CDK4/6 inhibition by abemaciclib dramatically reduced YAP1 expressions while concurrently upregulating cleaved‐poly(ADP‐ribose) polymerase‐1 (PARP1) levels in tumor samples from saline‐treated mice." (PMID 39968498, 2025). "Simultaneously, YAP1 is also capable of modulating metastasis through its influence on the tumor microenvironment (TME)." (PMID 40388100, 2025). "In the tumor parenchyma, the proportion of YAP1-positive cells was positively correlated with the proportion of CD4-positive cells and FOXP3-positive cells (r = 0.732, P = 0.004; r = 0.5780, P = 0.03)." (PMID 40051494, 2025). "Strikingly, combining Remodelin with the YAP1 inhibitor Verteporfin synergistically augmented anti-PD-1 efficacy, significantly suppressing tumor growth in immunocompetent mouse models." (PMID 40860183, 2025). "The YAP1 protein has also been suggested to promote an immunosuppressive tumor microenvironment by affecting regulatory T cells and macrophages." (PMID 40723817, 2025).
tumor (continued). "Considering these findings, our results demonstrate that using miR-142-3p or siYES1 presents a promising approach to inhibit YAP1 activation and its nuclear localization, offering a potential strategy to disrupt tumor growth." (PMID 40362400, 2025). "Unlike other TEAD inhibitors discussed, ION537 is an antisense oligonucleotide that selectively targets YAP1 to cause a marked reduction in YAP1 protein level in HCC and HNSCC tumor models." (PMID 41347094, 2025). "Emerging evidence demonstrates that YAP1 upregulation of various solid cancer is positively correlated with tumor progression and poor survival outcomes." (PMID 39827153, 2025). "Some SCLC subtypes rarely showed ASCL1 or NeuroD1 mutations but rather expressed others, including those derived from the coding of YAP1 and POU2F3, which are related to the loss of neuroendocrine characteristics of the tumor." (PMID 40422520, 2025). "The pro-CAF and pro-tumor roles of the YAP1–SRC–FAP/α-SMA axis were further supported in mouse co-implantation models and human-derived NF/CAF systems." (PMID 41514658, 2025). "By chi-square test, we found that COPB2 expression was significantly associated with tumor size and TNM staging in HCC patients, and YAP1 expression was significantly correlated with the degree of tumor differentiation and TNM staging in HCC patients." (PMID 40191726, 2025). "JQ1 mainly targets tumor cells with high YAP1 expression and treatment resistance and can inhibit radioresistant cells with strong cancer stem cell characteristics and invasive phenotype." (PMID 40723817, 2025). "Co-expression of POU2 F3+/YAP1+ within a tumor has been described as the second most common combination following ASCL1+/NEUROD1+." (PMID 40500731, 2025). "The regulatory components upstream of YAP1 and TAZ are considered tumor suppressors, whilst YAP1, TAZ, and TEAD1-4 are proto-oncogenes." (PMID 40301543, 2025). "Mechanistically, CDK4/6 directly phosphorylates DUB3, enhancing its deubiquitinase activity towards YAP1, which promotes tumor growth and contributes to chemo-resistance in HCC." (PMID 40307228, 2025). "In non-small cell lung cancer (NSCLC), HIF-1α-mediated suppression of the Hippo pathway leads to YAP1 activation and subsequent ferroptosis inhibition, suggesting a potential mechanism for tumor cell survival under hypoxic conditions." (PMID 40977060, 2025). "Subcellular localisation of Yap1 was assessed by immunohistochemistry in tumor sections of Gp130FF mice, revealing increased nuclear Yap1 localization indicative of increased transcriptionally active Yap1." (PMID 37957015, 2024). "Conversion of M2-to-M1-like polarized MФs through Yap1 activation inhibits tumor progression and contributes to developing potential TAMs-targeted immunotherapies in combating EOC peritoneal metastases." (PMID 39198883, 2024). "Secondly, dihydroartemisinin improves the immunosuppressive TME-induced immune escape by inhibiting YAP1, which leads to decreased PD-L1 expression in liver tumor cells and increased tumor-infiltrating CD8+T cells." (PMID 38550587, 2024). "YAP1 has been shown to contribute to inducing immunosuppressive TME by upregulating PD-L1 or stimulating cytokines such as CXCL5 from tumor cells to recruit tumor-infiltrating macrophages, myeloid-derived suppressor cells (MDSCs) and Tregs cells." (PMID 38659003, 2024). "In our in vivo experiments, we further confirmed that TAM-EVs enhanced HNSCC angiogenesis and tumor growth through the miR-21-5p/YAP1/HIF-1α axis." (PMID 38602536, 2024). "Subsequent pathway enrichment studies highlighted activation of the HIPPO/YAP1 signaling axis, along with the induction of numerous tumor-intrinsic cytokines." (PMID 37968341, 2024). "Loss of YAP1 in CD4+ and CD8+T cells enhanced T cell activation, differentiation, and cytotoxic function against tumor cells." (PMID 38550587, 2024).
tumor (continued). "Immunohistochemistry (IHC) assessments of YAP1 and Lats1 protein levels in 54 human tumor sections of ccRCC and normal renal tissues revealed prominent YAP1 nuclear immunoreactivity in the proximal tubules of ccRCC tumors compared to the normal kidney." (PMID 39123485, 2024). "Previous studies have reported the overexpression of YAP1 in human cancer and revealed a relationship between higher expression or activity of YAP1 and worse patient prognoses in various tumor entities." (PMID 38444414, 2024). "When the initial tumor size is similar, the tumor produced by the YAP1 phase separation of defective cells is more sensitive to PD-1 therapy." (PMID 38550587, 2024). "Several studies have reported that hypoxia stimulates the expression of Yes1 associated transcriptional regulator (YAP1), which is implicated in tumor progression." (PMID 39030638, 2024). "To more accurately quantify the effects of Yap1 deletion in tumor cells on the tumor immune environment in vivo, we used flow cytometry to assess the abundance of various effector cells." (PMID 37957015, 2024). "YAP1 suppresses the anti-tumor response facilitated by suppressing the cytotoxicity of activated CD8+T cells." (PMID 38550587, 2024). "During tumor development, YAP1 phosphorylation is inhibited, and its downstream regulators YAP1 and TAZ enter the nucleus, where they increase the transcriptional activation of genes involved in cell proliferation and metastasis." (PMID 39531326, 2024). "Collectively, our data suggest that altered Yap1 expression in tumor epithelium alters the composition and activity of the immune environment to possibly promote anti-tumor immune responses." (PMID 37957015, 2024). "Our IMC-based tissue remodeling analysis further showed significantly upregulated YAP1 expression within the microenvironment of S3, both in stromal and tumor cells, compared with other FB clusters." (PMID 39759522, 2024). "By RT-qPCR, we revalidated the expression of CXCLs (CXCL2, CXCL3, CXCL5, CXCL10) in MB49 YAP1-Sh clones and tumor tissues from VP-treated mice bearing UCB cell–derived xenografts." (PMID 39630608, 2024). "The pharmacodynamic analysis also showed a decrease in YAP1 expression at protein and transcript level in the tumor tissue taken from the VP-treated animals." (PMID 39630608, 2024). "Diacylglycerol lipase α (DAGLA) induces tumor cells to produce free FAs, enhances YAP1 activity, and aggravates the malignant phenotype and tumor progression in HCC." (PMID 38550587, 2024). "Mechanistically, CSN6 antagonizes speckle‐type POZ protein (SPOP) ubiquitin ligase to stabilize HMGCS1, which in turn activates YAP1 to promote tumor growth." (PMID 38308184, 2024). "Glycolysis is necessary to maintain the tumor-promoting function of YAP1, and YAP1 is needed to give full play to the growth-promoting activity of glucose." (PMID 38550587, 2024). "Considering YAP1 functions as a sensor in the tumor microenvironment, we performed a metabolic analysis, which showed that uracil metabolism was significantly enriched with UMP, uracil, uridine, and UDP‐GlcNAc decreasing after TRIM65 knockdown." (PMID 39005234, 2024). "The results of IF staining showed that the expression of YAP1 was significantly increased in KDELR1-kd tumor xenograft." (PMID 39715773, 2024). "Taken together, these data showed that CSN6‐HMGCS1 axis regulates mevalonate metabolism, promoting YAP1 nuclear translocation and transcriptional activity to facilitate tumor progression." (PMID 38308184, 2024). "In one study, YAP‐1 expression correlated with advanced tumor stage, especially in cisplatin‐resistant NBs, and YAP‐1 was shown to support tumorigenesis and invasion." (PMID 38925618, 2024).
tumor (continued). "Our previous work linked the intrinsic oncogenic functions of the transcriptional coregulator Yes-associated protein 1 (YAP1), the central Hippo pathway effector, to UPS cell proliferation, tumor growth, and reduced human patient survival." (PMID 38652549, 2024). "In animals with well-established disease, ablation of Yap1 activity significantly reduced tumor size to inhibit cancer progression." (PMID 37957015, 2024). "The RT-qPCR analysis showed significantly decreased expression of CSC-associated markers and CXCL genes in tumor tissues of the STAT3 inhibitor–treated group, which appeared similar to YAP1 attenuation in these cell lines." (PMID 39630608, 2024). "In order to transfer these findings into a more complex model, the influence of BAG3/YAP1‐signaling on tumor growth was validated in an OTC transplantation model." (PMID 38655699, 2024). "In human colorectal cancer, STAT3 is required for YAP1 activation, and they cooperate to regulate tumor angiogenesis." (PMID 38481347, 2024). "Conversely, the expression or activity of YAP1 in HCC is also regulated by the lipid metabolism of tumor cells." (PMID 38550587, 2024). "Residual ANTXR1 + myCAFs after chemotherapy inhibited anti-tumor immunity via the YAP1 signaling pathway." (PMID 39335478, 2024). "Taken together, our data demonstrate that CSN6 promotes YAP1 nuclear translocation and YAP1 transcriptional activity to facilitate tumor growth." (PMID 38308184, 2024). "Here, we show that reduced expression of Yap1 in Yap1KD; Gp130FF tumor organoids reduces their capacity to produce IL-11, whereas Yap1 deletion reduces proliferation and survival of neoplastic cells in tumors of Gp130FF; Yap1KO mice." (PMID 37957015, 2024). "The injection of NK cells can improve the death of tumor cells and inhibit the expression of YAP1, thereby reducing the tumor growth rate." (PMID 38550587, 2024). "Correlation between the native immune response and the expression of antigen-presenting genes of each tumour subtype indicates that only the expression of YAP1 positively correlates to cGAS, STING, HLA-E and other interferon-inducible genes." (PMID 39215193, 2024). "After approximately two weeks, disseminated tumor cells were concomitantly detectable, and Yap1−/− mice displayed a higher tumor growth rate than WT mice." (PMID 39198883, 2024). "The pathways involved in the neuroendocrine-low differentiation of SCLC tumors, including YAP1, NOTCH, Wnt family (WNT), and MYC, have each been implicated in tumor progression and treatment resistance across various cancers." (PMID 39456533, 2024). "The recruitment of NK cells by CD4+ T cells to mediate anti-tumor response is MHCI independent, suggesting multiple co-ordinated anti-tumor immune responses activated as a result of Yap1 depletion in the tumor epithelium." (PMID 37957015, 2024). "Increasing the circNOTCH1 promotes G protein‐coupled oestrogen receptor‐induced tumour growth through YAP1/TEAD signalling in non‐small‐cell lung cancer." (PMID 38159063, 2024). "A consistent result was obtained from the removal of Lat A, an agent that softens cells, in Lat-treated YAP1-KO tumor cells." (PMID 38360940, 2024). "Recent studies have highlighted the heightened presence of YAP1 in invasive tumor cells and its pivotal role in their proliferative and invasive abilities." (PMID 38540274, 2024). "In cSCC models, it was found that FAT1 deletions promote tumor initiation and progression, and increase YAP1 expression, promoting a mesenchymal state within the tumor tissue." (PMID 39199674, 2024). "YAP1 is activated in the development and progression of liver tumor, which drives tumor cell survival, proliferation, invasive migration, metastasis, and stemness of liver tumor cells." (PMID 38550587, 2024). "We then observed that injection of CRC cells overexpressed KLF15 increased the expression of KLF15 and LINC00689 in tumor tissues, while decreased YAP1 and β-catenin levels." (PMID 38273088, 2024).
tumor (continued). "We found that Yap1 was predominantly expressed in normal gastric epithelial and tumor epithelial cells, with lower expression also found in cancer-associated fibroblasts and endothelial cells." (PMID 37957015, 2024). "Mechanistically, UHRF1 binds to YAP1 (the major downstream effector protein of the Hippo signaling pathway) and inhibits the ubiquitination-dependent protein degradation, thereby stabilizing YAP1 protein in tumor cells of SCLC." (PMID 38725075, 2024). "Since Sox9 deletion decreases survival in Akt-YAP1 mice with a larger tumor burden, we next sought to evaluate tumor cell death and proliferation through histologic observation." (PMID 39273023, 2024). "In summary, inhibiting the activity of YAP1 enhances the activation, differentiation, and cytotoxicity of T cells, hinders the differentiation of Tregs, and suppresses tumor growth." (PMID 38550587, 2024). "Another study pointed out that elevated YAP1 in CAFs increases the growth of tumor epithelial cells in prostate cancer and originates the secondary metastasis." (PMID 38361941, 2024). "Due to YAP1 plays multiple roles in different cells of liver tumor, including tumor cells and immune cells, there will be a continuing important role for YAP1 in the field of tumor immunology, especially in the exploration of tumor immunotherapy." (PMID 38550587, 2024). "These YAP1 fusions constitute an alternative to NF2 loss and are oncogenic when expressed in mice, suggesting that they are the likely tumor-initiating events and oncogenic drivers in these tumors." (PMID 38571886, 2024). "Two sites in Yap1 targeted by Lats kinases in the Hippo tumor suppressive pathway, Ser94 and Ser112 (equivalent to Ser109 and Ser127 in human YAP1), were reduced, implying Yap1 activation in both males and females." (PMID 38672675, 2024). "In preclinical models of Kras-driven pancreatic ductal adenocarcinoma, tumor progression has been functionally linked to the concomitant activity of LIF-1, YAP1, and TAZ." (PMID 37957015, 2024). "These YAP1-induced changes in tumor microenvironment and metabolic reprogramming promote the progression of HCC and the inefficacy of ICI therapy." (PMID 38550587, 2024). "The biological role of RP11–323N12.5 in tumor growth and immunosuppression through YAP1 was also established in vivo." (PMID 38226210, 2024). "It is believed that reciprocal interactions between YAP1 activity in CAFs and tissue stiffness and mechanical stress in the tumor microenvironment drive a continuous process of maintaining CAF phenotypes and malignancy." (PMID 38308096, 2024). "The high expression of YAP1 in tumor tissue can lead to the depletion of CD8+T and CD4+T cells, facilitating the proliferation and dissemination of liver tumor cells." (PMID 38550587, 2024). "The in vivo experiments further proved that miR-21-5p carried by TAM-EVs promoted the process of tumor angiogenesis via YAP1/HIF-1α axis in HNSCC." (PMID 38602536, 2024). "This study improves our understanding of the molecular mechanism of TAM-EVs in tumor angiogenesis and identifies the miR-21-5p/YAP1/HIF-1 axis as a potential therapeutic target for HNSCC." (PMID 38602536, 2024). "The elevated expression of YAP1 has been shown to facilitate tumor cell proliferation, suppress apoptosis, promote cell migration and invasion, and enhance self-renewal of stem cells." (PMID 38227081, 2024). "Analysis of whole tumor protein lysates by Western blots demonstrated reduced levels of total and phosphorylated Yap1 and Stat3 in Gp130FF; Yap1KO compared with Gp130FF; Yap1WT mice." (PMID 37957015, 2024). "Currently, much is known about the regulation of YAP1 in metabolic reprogramming of tumor cells, but little is known about the regulation of YAP1 on metabolic reprogramming of immune cells in liver tumor." (PMID 38550587, 2024).